SNORA36A (small nucleolar RNA, H/ACA box 36A)
Synonyms: ACA36
Gene: Small nucleolar RNA gene on chromosome X (154,768,528 to 154,768,659, forward strand). Ensembl gene ENSG00000206948.
Gene Ontology:
Biological process: RNA processing
Cellular component: nucleolus
Homologues: Orthologues: macaque SNORA36A (98% identical), rabbit SNORA36A (83% identical), pig SNORA36A (79% identical). Paralogues in human: SNORA36C (97% identical), SNORA36B (87% identical).